CCL1 (C-C motif chemokine ligand 1)
Diseases named in the same sentence as CCL1 in open-access papers (continued):
Sharing a sentence is not in itself a finding about the gene and the disease.
neurodegenerative disease (2 papers, 2022 to 2025). A disorder of the central nervous system characterized by gradual and progressive loss of neural tissue and neurologic function. "The results of the present study showed that Tbx20 was positively correlated with CCL1, suggesting that Tbx20 could regulate immunity and participate in the development of neurodegenerative diseases." (PMID 36279395, 2022).
neurological disorders (2 papers, 2023 to 2024). "Many studies reported increased activity of CCL1 in research models and patients suffering from neurological disorders." (PMID 37765263, 2023).
bacterial infection (1 paper, 2022). "Studies have shown that changes in chemokines and chemokine receptors play an important role in the inflammatory response to AD, in which CCL1 and CCR8 prevent bacterial infection from participating in the demyelination of AD." (PMID 36279395, 2022).
kidney (1 paper, 2026). "Renal vasculitis correlated with kidney PD-1, CCL1, MIF, Granzyme A, IL-15, and BAFF." (PMID 42182101, 2026).
respiratory diseases (1 paper, 2023). "This is in accordance with previous reports showing elevated inflammatory markers (eg, CRP, IP-10, IFN-γ, CCL1, and VEGF) in unstimulated plasma or serum in active TB compared to LTBI or other respiratory diseases regardless of HIV-1 status." (PMID 36998631, 2023).
CCL1 also shares sentences with these, for which no sentence is quoted: prostate carcinoma (3 papers); allergic rhinitis (2); Alzheimer disease (2); hepatocellular carcinoma (2); acute myeloid leukemia (1); acute pancreatitis (1); airway hyperresponsiveness (1); Autoimmunity (1); bladder transitional cell carcinoma (1); bone cancer (1); carcinoma in situ (1); cardiovascular diseases (1); cholestasis (1); chronic myeloid leukemia (1); colon cancer (1); coronary heart disease (1); Crohn disease (1); depression (1); diabetic eye disease (1); diabetic nephropathy (1); diabetic neuropathy (1); diarrheal disease (1); eosinophilia (1); experimental autoimmune encephalomyelitis (1); fungal infections (1); gingivitis (1); glomerulonephritis (1); infectious disease (1); insomnia (1); ischemic stroke (1).
A further 14 diseases each share a sentence with CCL1 in 1 paper.